IL6 (interleukin 6)
Diseases named in the same sentence as IL6 in open-access papers (continued):
Sharing a sentence is not in itself a finding about the gene and the disease.
COVID-19 (continued). "Like the laboratory parameters of cancer patients with COVID-19, the median expression levels of CRP, mg/L (10.95, IQR [1.55–43.18]), and IL-6, pg/ml (12.30, IQR [5.48–28.22]) in COVID-19 patients without cancer were significantly higher than the upper limit of the normal reference range." (PMID 33192519, 2020). "Furthermore, they describe a positive correlation between the proportion of IL-6-producing CD4 + T cells and granulocyte-macrophage colony-stimulating factor (GM-CSF) and the severity of cases of COVID-19." (PMID 32967329, 2020). "As expected, higher plasma levels of pro-inflammatory cytokines IL1β, IL6, IL8, and TNFα at admission and before specific treatment were positively correlated with the severity of COVID-19 symptoms (p < 0.0001 for all cytokines), confirming the results from previous studies." (PMID 33585507, 2020). "Given the patterns of COVID-19 pathology and immune dysregulation, it may be logical to defer TCZ until the inflammatory phase due to the positive effects of IL-6 release in the acute infection stage which theoretically prevents SARS-CoV-2 proliferation." (PMID 33194450, 2020). "Research has demonstrated that a higher IL-6 level on admission can predict greater odds of complications and illness severity in COVID-19 patients; however, mortality was not evaluated." (PMID 32765283, 2020). "In our study, cytokines including IL-1β, IL-6, IL-10, and TNF-α were elevated in severe COVID-19 and active AOSD, compared with healthy controls, indicating the potential contribution of cytokine storm in pathogenesis of COVID-19 and AOSD." (PMID 33552062, 2020). "By using LASSO regression analysis, we further identified risk factors for the development of sepsis and found that changes in platelet counts, CRP, IL-6, BUN, and CK levels might be useful for predicting the incidence of viral sepsis among COVID-19 cases." (PMID 33178716, 2020). "In an older, sedentary population (61–66 years), 6 months of both AE and RE resulted in increased circulating levels of anti-inflammatory IL-10 and reduced levels of IL-6, CRP, and TNF-α, which are all involved in the cytokine storm observed in severe cases of COVID-19." (PMID 33001410, 2020). "Additionally, the proinflammatory markers IL-6, ferritin, LDH and CRP, drawn on admission or on day of COVID-19 diagnosis for patients already hospitalized at the time of positive PCR, were associated with higher odds of intubation by univariate analysis." (PMID 33351817, 2020). "Compared with COVID-19 without pneumonia, COVID-19 with pneumonia had significantly higher serum IL-2R, IL-6, and TNF-α." (PMID 32727465, 2020). "Reports also suggest that in certain instances, patients with severe COVID-19 were found to exhibit higher levels of pro-inflammatory cytokines such as IL-2R, IL-6, IL-8, IL-10, and TNF-α compared to patients with non-severe condition." (PMID 33120941, 2020). "As of now, four clinical trials are recruiting patients with COVID-19, severe acute respiratory failure, and CRS, aiming at evaluating the safety and effectiveness of anakinra alone or in combination with anti-IL-6 agents (NCT04330638, NCT0432402, NCT04357366, NCT04339712)." (PMID 32397174, 2020). "Furthermore, there is emerging evidence of the importance of pro-inflammatory cytokines interleukin-6 (IL-6) and tumour necrosis factor (TNF-alpha) as predictors of mortality in patients with COVID-19 and that IL-6 blockade appears to be beneficial." (PMID 32933530, 2020). "All hospitalized pediatric patients diagnosed with COVID-19 should undergo the following laboratory tests on admission: blood count with reticulocytes, inflammatory markers (CRP, ESR, IL-6, ferritin), prothrombin time, activated partial thromboplastin time (APTT), fibrinogen, and D-dimer." (PMID 33331400, 2020).
COVID-19 (continued). "Among the elevated levels of inflammatory mediators in COVID-19 patients, the blood levels of IL-6 are noticeably higher in non-survivors compared to survivors and predict the need for mechanical ventilation." (PMID 33014208, 2020). "Compared with COVID-19 without pneumonia, COVID-19 with pneumonia had significantly higher serum interleukin (IL)-2R, IL-6, and tumor necrosis factor (TNF)-α." (PMID 32727465, 2020). "We revealed that COVID-19 patients with pneumonia had significantly higher levels of serum IL-2R, IL-6, and TNF-α than COVID-19 patients without pneumonia." (PMID 32727465, 2020). "COVID-19 patients displayed similar T-cell exhaustion to non-COVID-19 patients, but with a more unbalanced inflammatory/anti-inflammatory cytokine response (IL-6/IL-10 and TNF-α/IL-10 ratios)." (PMID 33272291, 2020). "Further, interleukin 10 (IL-10), interleukin 6 (IL-6), interleukin 1 (IL-1), interleukin 2R (IL-2R), and tumor necrosis factor alpha (TNF-α) levels might exceed the upper limit in COVID-19 patients." (PMID 32516940, 2020). "However, we saw only IL-6 was no longer significant in the comparison between acute and long COVID-19 (12 + 16 + 20 M merged) after adjusting to BMI." (PMID 40335840, 2025). "In our pooled analyses, IL-6 was significantly higher in COVID-19 patients with pneumonia compared to those without pneumonia (SMD = 0.34, 95% CI 0.17–0.52, p < 0.0001), and also higher in COVID-19 pneumonia cases compared to healthy controls (SMD = 0.49, 95% CI 0.31–0.68, p < 0.00001)." (PMID 41585373, 2025). "Studies have established that increased levels of IL-1β, IL-2, IL-6, IL-10, IFN-γ, TNF, IFN-γ-inducible protein 10 (IP-10), granulocyte macrophage-colony stimulating factor (GM-CSF), and monocyte chemoattractant protein-1 (MCP-1) correlate with COVID-19 severity." (PMID 39940907, 2025). "This meta-analysis provides robust evidence that inflammatory biomarkers, particularly IL-6, IL-10, IL-8, and S100B, are significantly elevated in patients with COVID-19 pneumonia and organ failure compared to non-pneumonia COVID-19 patients and healthy controls." (PMID 41585373, 2025). "The clinical worsening of individuals with COVID-19 may be related to immunopathological damage, reflected by increased concentrations of proinflammatory cytokines such as tumor necrosis factor alpha (TNF-α) and interleukin 6 (IL-6)." (PMID 41394849, 2025). "The presence of phosphorylated STING and high levels of ISGs and pro-inflammatory cytokines such as IL-1, IL-6, and TNF- α, especially in IFN-β-producing perivascular macrophages and damaged endothelial cells, were demonstrated in skin lesions of patients with moderate to severe COVID-19." (PMID 40649826, 2025). "Another limitation is the limited number of cytokines analyzed, as only IL-6 and IL-10 were measured, which may not fully reflect the complexity of the immune-inflammatory response in COVID-19." (PMID 41203712, 2025). "Bulk RNA-seq analysis revealed that lungs and adipose tissue specimens had various immune cells and inflammatory markers (e.g., IL-6) upregulated in COVID-19–infected obese K18 mice (n=4) as compared with COVID-19–infected normal or non-obese (n=4) control mice." (PMID 41488148, 2025). "To date, IL-6 levels have not been evaluated in ambulatory patients concurrently presenting with COVID-19 and periodontal disease, nor has their relationship with the pathognomonic symptoms of COVID-19 been investigated." (PMID 40647649, 2025). "Notably, interleukin-6 (IL-6) and tumour necrosis factor were identified as hub cytokines connecting SLE to COVID-19 infection, while IL-6 and interleukin-10 (IL-10) were pivotal in connecting SLE to COVID-19 severity." (PMID 40643149, 2025).
COVID-19 (continued). "Consequently, the administration of BDs of the mRNA COVID-19 vaccine was found to be safe, although transient alteration of systemic inflammation status is expected as a result of T cell priming (IL2-R, IL-6, TNF-α), followed by the deactivation (IL-10) of pro-inflammatory cytokine synthesis." (PMID 40266144, 2025). "Additionally, known stress-induced cytokine surges (e.g., IL-6, TNF-α) or microcirculatory impairment during acute COVID-19 could impact follicular health in a patient-specific manner." (PMID 41298780, 2025). "Moreover, patients with MIS typically present very high levels of circulating inflammatory biomarkers (C-reactive protein [CRP], IL-6, ferritin), generally higher compared to those found in patients with COVID-19 without MIS." (PMID 39775145, 2025). "Interestingly, only IL-6 showed significant correlation with markers of fibrinolysis in the COVID-19+ group, including a significant negative correlation with FXIII-B and with plasminogen levels and a moderate, significantly positive correlation with D-dimer." (PMID 40303405, 2025). "The clinical course of COVID-19 ranges from mild symptoms to severe complications, and common laboratory markers such as D-dimer, ferritin, interleukin-6 (IL-6), and C-reactive protein (CRP) often do not accurately predict which patients will develop severe disease." (PMID 40702494, 2025). "The assessment of serum concentrations of IL-6 revealed that in all tested groups, the mean levels of this cytokine were above the normal limit (>1.9 pg/mL); In the PIMS group, the levels were the highest, in INFLAM, they were intermediate, whereas in COVID-19, they were the lowest." (PMID 39940694, 2025). "EVs from SARS-CoV-2–infected cells contain viral proteins, like the nucleocapsid and spike proteins, and are enriched with integrins and immune signaling molecules, such as IL-6 and TGF-β, which may contribute to the cytokine storm observed in severe COVID-19 cases." (PMID 39862905, 2025). "It is hypothesized that myocardial damage during COVID-19 may occur through two mechanisms: (a) Cytokine storm manifested by increased ferritin, lactate dehydrogenase (LDH), interleukin (IL)-6, and D-dimer, accompanied by increased high-sensitivity troponin I values." (PMID 40075869, 2025). "Additionally, a large RCT done in 342 COVID-19 patients with signs of cytokine release syndrome found that drugs targeting IL-1 (anakinra) or IL-6 (tocilizumab or siltuximab) did not shorten the time to clinical improvement." (PMID 40333142, 2025). "Besides the role in supporting viral replication, MAPK3 hyperactivation can trigger inflammation (e.g., IL-6, TNF-α) and lung epithelial damage, central to severe COVID-19, and today, MAPK pathway inhibitors are under investigation to mitigate inflammation and viral replication." (PMID 41227320, 2025). "Compared to patients with COVID-19 who do not have diabetes, those with diabetes had heightened inflammatory responses (characterized by elevated neutrophils, serum ferritin, IL-6, CRP, and erythrocyte sedimentation rate) and suppressed immunity (marked by significantly reduced lymphocyte levels)." (PMID 41426569, 2025). "Furthermore, zinc levels were negatively correlated with IL-6 in both the COVID-19 patient groups that did not require hospitalization and the control group, but the correlation was not statistically significant." (PMID 40756075, 2025). "IL-6/JAK–STAT3 inhibitors, IL-1 blockers, and strategies targeting CCR2/CCR5 are under investigation in oncology and may, with careful selection, have dual relevance in patients with prior severe COVID-19 and inflammation-dominated tumor microenvironments." (PMID 41440526, 2025). "In our study, we found that the interleukins primarily involved in TEN were IL-4, IL-6, and IL-12, which were modulated (downregulated) by TEN, along with augmented IL-1α, IL-1β, IL-5, IL-8, NF-κβ, and interferons (IFN; α, β, and γ), which were modulated by COVID-19." (PMID 39941142, 2025).
COVID-19 (continued). "This leads to the upregulation of pro-inflammatory cytokines such as Interleukin-6 (IL-6), TNF-α, and IL-1β and contributing to the cytokine storm, a hyperinflammatory state characterized by the uncontrolled systemic release of cytokines and pulmonary pathology seen in critical COVID-19 patients." (PMID 41176818, 2025). "The expression levels of a 13-cytokine panel (IL-1α, IL-1β, IL-2, IL-4, IL-5, IL-6, IL-8, IL-10, IL-12, NF-κβ, and IFN-α, IFN-β, and IFN-γ) were measured by qRT-PCR from peripheral blood mononuclear cells (PBMC) obtained from the patient with TEN and their parents (which were positive for COVID-19)." (PMID 39941142, 2025). "In this sense, a meta-analysis carried out in 2020 that evaluated 8719 COVID-19 patients with severe disease found that those patients hospitalized in the ICU had elevated levels of acute phase reagents, such as erythrocyte sedimentation rate, CRP, IL-6, and IL-10, among others." (PMID 40756075, 2025). "Severe COVID-19 in controls, but not SOT recipients, was associated with a marked increase in several canonical proinflammatory serum cytokines and chemokines (e.g., IL-6, CCL23, and CXCL8)." (PMID 39794319, 2025). "The increase in IL-6, IL-12, and TNF-α levels in HUVEC supernatants further supports our hypothesis regarding the dynamic regulation of inflammatory mediators in response to COVID-19." (PMID 41583455, 2025). "Patients with COVID-19 and Self-RPD+ may experience sneezing, which leads to the dissemination of contaminated saliva and nasal secretions, promoting an increased SARS-CoV-2 viral load and the accumulation of soluble IL-6." (PMID 40647649, 2025). "Consequently, persistent elevations of IL-6 and TNF-α—often seen in patients with severe COVID-19—may substantially contribute to accelerated cellular aging through both telomere erosion and diminished telomere maintenance." (PMID 41154334, 2025). "Furthermore, increased expression of the IL-6 receptor (IL-6R) and higher levels of IL-6 have been observed in COVID-19 patients who did not survive compared to patients who survived throughout the clinical course of the disease." (PMID 40406515, 2025). "Interestingly (and in our opinion importantly), the analyses here found that COVID-19 patients with chronic CVD co-morbidities had a significantly lower IL-6 concentration than COVID-19 patients with no co-morbidities (adjusted p = 0.021)." (PMID 39518552, 2024). "As COVID-19 severity increased, there were corresponding rises in infection indicators like white blood cell (WBC) count, neutrophil to lymphocyte ratio (NLR), C-reactive protein (CRP), serum amyloid A (SAA), and inflammatory mediators such as interleukin-6 (IL-6) and interleukin-10 (IL-10)." (PMID 39081794, 2024). "While IL-6 is considered an immunosuppressive cytokine that helps prevent excessive inflammation, high levels of IL-6 in the serum of non-surviving COVID-19 patients may signal an overactive immune response, potentially leading to adverse outcomes." (PMID 39654886, 2024). "However, although we found that IL-6 expression increased during the course of mild-to-severe COVID-19 transformation, there was no significant change in severe-to-mild transformation." (PMID 38710800, 2024). "The phenomenon, called post-acute sequelae of COVID-19 (PASC), may be more closely linked to persistent cytokine dysregulation, including sustained IL-1β activity and elevated levels of IL-6 and TNF-α, rather than the emergence of post-COVID-19 autoantibodies." (PMID 39518964, 2024). "In contrast to IL-6, we observed no increase in serum levels of IL-11 in COVID-19 patients." (PMID 39835136, 2024). "It is well established that viral infections such as COVID-19 are characterised by increases in pro-inflammatory cytokines such as IL-6, TNF-α, IL-12p40, and IL-23, while influenza and HIV-1 infections are characterised by increased production of IL-1β, IL-6, and TNF-α." (PMID 39123583, 2024).
COVID-19 (continued). "Interestingly, we found stimulated IL-6 performed better in diagnosing BRD compared to another study assessing both serum IL-6 and C-reactive protein (CRP) for diagnosis of severe COVID-19, for which an AUC of 0.82 and 0.74 and a YI of 63% and 42% respectively." (PMID 39541407, 2024). "This complex interplay suggests that PRL may modulate the immune response in COVID-19 in a manner that is not directly captured by static measurements of IL-6 but which becomes apparent through dynamic changes over time and in the context of disease severity." (PMID 39595974, 2024). "As a result, IL-6 may serve as both a biomarker and a therapeutic target for COVID-19, particularly in the absence of direct-acting antiviral treatments." (PMID 39458339, 2024). "COVID-19 patients who had chronic cardiovascular co-morbidities and administered statins or renin–angiotensin–aldosterone system inhibitors had significantly lower plasma concentrations of IL-6 than COVID-19 patients who did not have any co-morbidities." (PMID 39518552, 2024). "Although the role of the exacerbated inflammatory response in developing clinical complications in patients with COVID-19 has been recognized from the beginning, and therapies directed against inflammatory mediators such as IL-1β and IL-6 have been proposed, the results have not yet been conclusive." (PMID 39637135, 2024). "Additionally, elevated levels of D-dimer, IL-6, and CRP in AIS patients with acute COVID-19 suggest that pre-stroke COVID-19 infection may contribute to increased secondary inflammation post-stroke onset." (PMID 38700338, 2024). "An observational cohort (n = 772) and a validation cohort (a subset of REMAP-CAP, n = 119) of critically ill patients with hypoxemic respiratory failure due to COVID-19 were analyzed, who either received no treatment, received steroids or received steroids plus IL-6 blocking agents." (PMID 38594746, 2024). "IL-6 and TNFα were involved in immunological processes that had a direct and indirect relationship with the activation of cytokines, including IL6 and TNF-a, and cytokine storm, and this indicates their role in the formation of problems and complications, including ARDS, in COVID-19 patients." (PMID 39118801, 2024). "There was some limited evidence of e-cigarette-induced IL6 and TNF downregulation, and NFκB1 upregulation, suggesting that vapers may be at a lower risk of developing severe COVID-19 versus smokers, but at increased risk versus nonsmokers." (PMID 38991709, 2024). "IL-6 is a proinflammatory cytokine related to disease severity and unfavorable outcomes such as ICU stay, ARDS, and severe disease; as a matter of fact, monoclonal antibody Tocilizumab is commonly prescribed to patients affected with the most severe forms of COVID-19." (PMID 38535062, 2024). "Due to the attenuated immune response of COVID-19 patients, particularly the reduced upregulation of monocyte CD80 expression and the suppressed release of key cytokines such as IL-6, TNF, IL-1a, and IL-1b, this may lead to a decreased ability to clear C. albicans in these patients." (PMID 38658823, 2024). "This implies that age does not significantly influence IL-6 expression in COVID-19 patients." (PMID 39201618, 2024). "It is reported that a 44-year-old woman with COVID-19 was admitted to the hospital with complaints of chest pain; cardiac magnetic resonance and myocardial biopsy were suggestive of myocardial fibrosis, and normal CRP levels suggested that IL-6 was involved in this process." (PMID 39444690, 2024). "Also, COVID-19 patients tended to have higher levels of CRP and IL-6." (PMID 38246829, 2024). "In fact, the optimal results of clinical trials with tocilizumab (an IL-6 inhibitor) in patients with severe and critical COVID-19 led to its approval by the U.S. Food and Drug Administration (FDA) and its inclusion in the current Guidance for the Management of Acute COVID-19 in Children." (PMID 39596272, 2024).